EGFR (epidermal growth factor receptor)
Diseases named in the same sentence as EGFR in open-access papers (continued):
Sharing a sentence is not in itself a finding about the gene and the disease.
cancer (continued). "Some studies also indicate that SGLT1 targeting agents (Phlorizin or RNAi) may act as a novel adjuvant therapy for cancer treatment via the disruption of SGLT1/EGFR interaction." (PMID 34439414, 2021). "Here, we have presented the effect of four such mutations, namely the L858R, D770-N771insNPG, ΔELREA, and A763-Y764insFQEA, all of which have been shown to increase the catalytic activity of EGFR in vitro and continuously signal the pathway, which stimulates cancer cell growth." (PMID 34319231, 2021). "Our results show low expression of EGFR which could potentially mean that EGFR cannot contribute to drug resistance and highlight the mechanism of low EGFR expression in these cancer cell lines." (PMID 34006939, 2021). "In addition to its extensively investigated role in cancer progression through modulation of the EGFR signaling pathway, ADAM17 regulates other features that are associated with the disease, which have been more recently characterized." (PMID 33579029, 2021). "CD44-HA interaction can modulate a variety of intracellular signaling by forming coreceptor complexes with many RTKs (e.g., EGFR) that induce oncogenic pathways involved in cancer cell invasion, migration, and metastasis in the human MCF7 and TamR breast cancer cells." (PMID 34976811, 2021). "A photo-activatable ternary complex consisting of multifunctional shielding material (MSM) with photosensitizer (PS)-conjugated chondroitin sulfate (CS) and PEI-based binary complexes containing EGFR-plasmid vector based-small hairpin RNAs (shRNAs) for CD44 targeted cancer therapy was developed." (PMID 34372067, 2021). "EGFR TKIs and neutralizing antibodies have been shown to induce autophagy in cancer cells." (PMID 34207383, 2021). "EGFR is overexpressed in many cancers to function as an oncogene." (PMID 34887764, 2021). "EGFR is a major player in one of the most important cancer growth related pathways." (PMID 34495991, 2021). "As important cancer regulatory nodes, EGFR and SRC also cross-talk with the PI3K/AKT pathway." (PMID 34819120, 2021). "Furthermore, crosstalk between integrin αvβ3 and the EGFR plays an important role in modulating cancer cell proliferation." (PMID 34359854, 2021). "EGFR is overexpressed in HNSCC and many other cancers, but whether EGFR controls YAP activation is still poorly understood." (PMID 34725466, 2021). "It has been shown that not only does EGF signaling promote EMT in OSCC cells, but also that the cancer cells which are undergoing EMT express considerably lower levels of EGFR and are less susceptible to EGFR targeted therapies, which leads to their chemotherapeutic resistance." (PMID 33889303, 2021). "Secondly, the activating of EGFR by AT1R leads to the increased expression of VEGF in both cancer cells and endothelial cells, and intratumoral endothelial cells are activated in either paracrine or autocrine manner, which contributes to angiogenesis in TME449,450." (PMID 33888679, 2021). "EGFR sialylation affected EGF-mediated cancer cell proliferation." (PMID 33827580, 2021). "In addition, immunostaining for more biomarkers has been used for identification of CTCs in specific types of cancer, such as EGFR in prostate cancer and HER2 in breast cancer." (PMID 33448107, 2021). "EGFR plays an important role in the etiology and progression of many carcinomas, including PC." (PMID 33937024, 2021). "Thus, Amphiregulin participates in cancer cell proliferation, migration, invasion, and angiogenesis in human carcinomas, so Amphiregulin was incriminated as a predictive biomarker of anti-EGFR therapy for most EGFR-driven carcinomas." (PMID 33906293, 2021). "La expresión de EGFR (HER1), D2-40 y P63 puede apoyar más el diagnóstico del carcinoma primario que el del metastásico 13; sin embargo, cuando la enfermedad se presenta con compromiso axilar, la investigación clínica y la correlación patológica son lo más recomendable." (PMID 34559489, 2021).
cancer (continued). "Therefore, a TCGA database search for growth factors involved in EGFR signaling correlated with BCAR1 expression was performed because EGFR drives proliferation and is a target for EGFR-directed antibody treatment in many carcinomas (especially CRC)." (PMID 34830244, 2021). "EGFR is involved in the differentiation, proliferation, and survival of various cancer cells and is thus related to a poor prognosis, shorter survival, aggressive growth, and invasiveness of cancers." (PMID 32560337, 2020). "Thus, resources provided here would be useful to all researchers who study negative regulators of growth during development and cancer in the context of activated EGFR and/or Yki and positive regulators of growth in the context of activated EGFR." (PMID 32737065, 2020). "In addition, EGFR has been proposed as an important molecular target for the treatment of cancer, which has promoted the development of EGFR pharmacological inhibitors." (PMID 33178610, 2020). "EGFR/Erk/Akt is an important growth signaling axis of the cancer cells." (PMID 32483443, 2020). "Cancer cells captured in area I and II were of the acinar and solid subtype, which were negative for both sensitizing and resistant EGFR mutation, whereas cells in area III were positive for both sensitizing and resistant mutations." (PMID 32093629, 2020). "Moreover, the close association between EGFR and PI3K/AKT/mTOR pathway has been highlighted in some cancer-related studies." (PMID 32231464, 2020). "Further studies are still required to explore whether BASP1 can regulate other RTKs through similar positive feedback, like EGFR, in the lipid raft for cancer progression and acquired TKI resistance." (PMID 33042262, 2020). "The use of NGS in this present study revealed that females, non-smokers, family history of cancer and adenocarcinoma patients had greater EGFR 19 deletion mutation rate, consistent with most previous reports." (PMID 32047821, 2020). "Affibodies has been one of the most frequently used targeting ligands for cancer imaging since affibodies for human epidermal receptor 2 (HER2) and epidermal growth factor receptor (EGFR) are well-studied cancer biomarkers and very robust with pico-molar sensitivity." (PMID 33003566, 2020). "The mechanisms by which EGFR is regulated by calcium and its modulators may vary between tissue and cancer types." (PMID 32575848, 2020). "Instead of being diminished, the EGFR activation signal was sustained by signaling bifurcation, cancer network crosstalk, and compensatory pathway activation, as there are several intertwined major cellular signaling pathways that are tightly regulated by active EGFR signals." (PMID 32846967, 2020). "This compound was chosen for further comprehensive experiments to offer a new insight into its molecular mechanisms of action including the determination of apoptotic activity in the HCT116 cell line and inhibitory effects on cancer related enzymes such as RTKs, in particular EGFR and COX-2." (PMID 33171861, 2020). "Cancer cells may adopt various strategies, such as amplified KIT signaling, increased EGFR phosphorylation, KRAS mutations oncogene, or increased NRG1 for activating HER2/3 kinases to survive crizotinib treatments." (PMID 32164629, 2020). "Of these selected DEGs, 23 were upregulated and 19 were downregulated in EGFR-mutant cancers." (PMID 32277151, 2020). "In comparison with parent cells with KRAS mutation alone, cells with concomitant EGFR mutation exhibited higher sensitivity to EGFR-tyrosine kinase inhibitors (TKIs) but not to conventional anti-cancer drugs." (PMID 32130260, 2020). "Increasing molecular knowledge about cancer spurred the development of drugs that could inhibit oncogenic signaling and kill the cancer cells, resulting in the first-generation EGFR-TKIs gefitinib and erlotinib." (PMID 32234966, 2020).
cancer (continued). "Exogenous and endogenous TRPV1 agonists, applied in conjunction with P2Y2 and EGFR antagonists, may therefore constitute a potential form of anti-cancer therapy." (PMID 32545311, 2020). "Nevertheless, current mainstream research is focused on the suitability of EGFR-TKIs for EGFR-WT cancers and whether these drugs can be combined with other drugs to enhance their efficacy." (PMID 33276757, 2020). "EGF receptor overexpression is observed in numerous cancers, including breast, lung, colon cancer, and squamous cell carcinoma; therefore, an attempt was made to assess the effect of prolidase on cell metabolism in conditions of EGFR overexpression." (PMID 32824561, 2020). "CDC42 and EGFR have been used as potential targets for angiogenesis and cancer therapies." (PMID 32545766, 2020). "Given the critical role of mTOR in oncogenic EGFR signaling function, we considered the possibility that mTOR may promote TF expression in EGFR-mutant cancers." (PMID 32923403, 2020). "Moreover, “EGFR-addicted” cancer cell lines, when induced to undergo EMT, become erlotinib-resistant in vitro." (PMID 32498343, 2020). "The EGFR/PI3K/AKT pathway is extensively studied in the field of cancer biology." (PMID 32802113, 2020). "This led us to speculate that 1,25(OH)2D3 may inhibit EGFR-TKI resistance by reducing cancer cell stemness." (PMID 32820157, 2020). "Exosomes derived from cancer cells are characterized by the expression of RTKs, EGFR, and HER-2." (PMID 32957534, 2020). "It is interesting to determine whether EGFR activation can induce cellular senescence in cancer cells." (PMID 32323422, 2020). "Our previous work has demonstrated that DYRK1A positively regulates EGFR/Met via regulating the expression and activation of STAT3, and that suppression of DYRK1A enhances the anti-cancer activity of EGFR-TKIs in wild-type EGFR NSCLC cells via inhibiting the STAT3 signaling pathway." (PMID 32587776, 2020). "Historically, the EGFR TKIs erlotinib and gefitinib showed clinical activity against the tumors exhibiting corresponding mutations and a similar activity was proved for the TKI crizotinib and ALK-rearranged cancers." (PMID 35582610, 2020). "The novel recombinant EGFR-targeting β-defensin Ec-LDP-hBD1 displays both selectivity and enhanced cytotoxicity against cancer cells by inducing mitochondria-mediated apoptosis and exhibiting high therapeutic efficacy against EGFR-expressing carcinoma xenografts." (PMID 33114695, 2020). "Cetuximab is a chimeric antibody used to target EGFR to treat EGFR-overexpressing cancers." (PMID 32977707, 2020). "EGFR is well recognized for its regulatory roles in cancer cell proliferation and survival." (PMID 32714745, 2020). "Therefore, we performed experiments to find possible new mechanisms of action of EGFR-TKIs to better guide the clinical application of EGFR-TKIs in cancer therapy." (PMID 31892990, 2020). "The last mentioned might be supported by a threefold difference in the frequency of EGFR mutations between LUSC and LUAD during a previous pan-cancer analysis." (PMID 33213447, 2020). "EGFR is reported to be involved in cancer, apoptosis, and skeletal and muscular disorders." (PMID 32851035, 2020). "Thus, the peptides are most likely not binding to antigens that are expressed by several different types of cancer, such as the Thomsen–Friedenreich (TF) antigen, galectin-3, or the epidermal growth factor receptor (EGFR)." (PMID 32380649, 2020). "Additionally, we assessed the role of PGRMC1 in key cancer-related signaling pathways including EGFR/HER2 and ERα signaling." (PMID 32660617, 2020). "Therefore, EGFR-TKIs are considered second-line treatment options for patients with EGFR-WT cancers." (PMID 33276757, 2020).
cancer (continued). "Two studies showed that EGFR inhibitors AG1478 and erlortinib significantly upregulated apoptosis induced by inorganic AsBD arsenite and arsenic trioxide on various cancer cells, via a suppression of EGFR phosphorylation and a substantial inhibition of phosphorylated-AKT levels." (PMID 32002123, 2020). "Several human tumors originate in the epithelium and exhibit high epidermal growth factor receptor (EGFR) expression, hinting that EGFR could be a target in cancer drug delivery systems." (PMID 33375558, 2020). "Overexpression of epidermal growth factor receptor (EGFR) is reported in many types of cancer." (PMID 32922954, 2020). "ErbB receptor tyrosine kinase inhibitors (EGFR-TKIs), often used in cancer chemotherapy, can inhibit EGFR signaling in intestinal epithelial cells and decrease the capacity for growth and repair of the intestinal epithelium, which will result in atrophy of intestinal mucosa and secretory diarrhea." (PMID 33381214, 2020). "Studies suggested that IGF1R and EGFR combinatorial therapy might constitute a promising approach for cancer." (PMID 32391121, 2020). "This feature makes EGFR a great target for cancer treatment." (PMID 32075083, 2020). "Importantly, the agonism of CBRs using nanomolar concentrations of ∆9-THC increased the proliferation of cancer cells through activation of MAPK via transactivation of EGFR." (PMID 32340151, 2020). "Given the critical involvement of mTOR in EGFR-mut cancers, it is possible that TF might be a molecular and functional target of mTOR complexes in these tumors." (PMID 32923403, 2020). "Under these conditions, EGFR inhibitors like Erlotinib 22 and AG-1478 66 are able to act as YAP/TAZ inhibitors and may be used for EGFR-driven cancers requiring YAP/TAZ transcription." (PMID 32206112, 2020). "EGFR protects cancer cells from apoptosis, facilitate invasion and promote angiogenesis." (PMID 32679899, 2020). "Recently, it was shown that EGFR inhibitor synergized with LXRα agonists in killing cancer cells; for example, LXR ligands combined with gefitinib could better suppress cell cycle progression in NSCLC cells." (PMID 33224867, 2020). "Moreover, we demonstrated that p120ctn down-regulation intersects and synergizes with EGFR overexpression to induce an aggressive and invasive cancer phenotype." (PMID 33112928, 2020). "These EGFR mediated signaling cascades together with the hyperactivation of the DNA repair system may lead to the therapy failure observed in cancer patients." (PMID 35047986, 2020). "Besides gefitinib, which is a first-generation receptor tyrosine kinase inhibitor (RTKI), there are several other FDA-approved EGFR-targeting drugs for treatment of different types of cancer whose antiviral potential still has to be elucidated." (PMID 33198108, 2020). "Cancer development is promoted by EGFR-induced cell growth, migration, and survival." (PMID 32170176, 2020). "Cell-to-ECM adhesion favors EGFR-dependent cancer proliferation." (PMID 32546182, 2020). "The inhibition of M2-type TAMs in EGFR-mut tumors is significant and may enhance efficacy of existing cancer immunotherapy." (PMID 32923403, 2020). "This study aimed to assay the predictive and prognostic effects of changes in platelet count on non-small cell lung cancer (NSCLC) patients receiving anti-EGFR targeted therapy, and to determine the anti-cancer efficacy of EGFR tyrosine kinase inhibitors (TKIs)." (PMID 33243184, 2020). "Because the extent of EGFR expression in GBM is highly associated with poor prognosis, the characterization of the functional heterogeneity found for this receptor in this type of cancer is highly wanted." (PMID 33238647, 2020). "However, most cancer patients treated with these drugs exhibit EGFR-TKI resistance within 9–14 months." (PMID 33092268, 2020). "H1975 cells (T790M, L858R) were mixed with cells from cancer-negative sputum, and EGFR mutations were detected." (PMID 32033355, 2020).
cancer (continued). "Therefore, the inhibition of EGFR signalling has been reported as an important target in cancer therapy." (PMID 33287803, 2020). "Allosteric SHP2 inhibitors such as SHP099 and SHP394 stabilize the closed auto-inhibited state, which effectively inhibit the RAS-MAPK signaling pathway in cancer cells driven by epidermal growth factor receptors (EGFR) and other RTKs and their growth in vitro and in vivo." (PMID 32076487, 2020). "In this review, we discuss significant advancements in EGFR-targeting immunoconjugates, including ITs and recombinant photoactivable ADCs, which serve as a blueprint for further developments in the evolving domain of cancer immunotherapy." (PMID 33014289, 2020). "EGFR alterations have been reported in several diseases, particularly, in cancer." (PMID 32823532, 2020). "The results indicate that ARL4C could be a “switch” between the EGFR path and the JAK2/STAT5/β-catenin path to maintain the proliferation, migration, and invasion of cancer cells when cells are exposed to Erlotinib and EGFR path is blocked." (PMID 33194732, 2020). "In addition, EGFR overexpression and decreased degradation were correlated with Src activity in cancer cells, leading to increased EGFR signaling in the presence of activated Src." (PMID 32545852, 2020). "EGFR activation is well known to promote survival of certain cancer cells." (PMID 32323422, 2020). "The loss of miR-146a-5p may strengthen the epithelial-mesenchymal transition (EMT) to accelerate cancer cells metastasis by modulating epidermal growth factor receptor (EGFR)/ERK pathway." (PMID 33317606, 2020). "In addition, CMTM7 also inhibits cancer cell growth and represses oncogenic EGFR signaling by promoting EGFR internalization and further suppressing the Akt signaling pathway." (PMID 32328181, 2020). "One of the criteria of the selection of potential biomarkers was the differential expression not only between cancer and normal BEAS-2B cell lines, but also between A549 and HCC827 LC cells different in mutation status of the EGFR gene, one of the major pathological parameters in LC." (PMID 32629833, 2020). "Above all, OSI loaded into liposomes composed of egg-PC showed higher antitumor efficacy against cancer cells with EGFR mutations than free OSI and did not affect the viability of normal lung fibroblasts." (PMID 33008019, 2020). "Functional analysis showed that the core therapeutic targets against TNBC were mainly involved in epidermal growth factor receptor (EGFR)-phosphatidylinositol 3-kinase (PI3K)-AKT signaling pathway to prevent cancer cell proliferation and angiogenesis, as well as to enhance cancer cell apoptosis." (PMID 33092442, 2020). "In a prespecified analysis among patients with EGFR-FISH+ cancers, OS was significantly improved in the cetuximab group (HR = 0.58 [0.39–0.86], P = 0.01): median OS of 11.8 months (95% CI: 8.6–13.5) and 6.1 months (95% CI: 4.2–8.7) in cetuximab and chemotherapy arms, respectively." (PMID 32793499, 2020). "Besides, EGFR can induce the expression of the PAF receptor, which can be activated by the PAF produced by LPCAT2 in EGFR-expressing cancer cells, in an autocrine mechanism, or surrounding cells in the microenvironment, in a paracrine fashion." (PMID 33392068, 2020). "Because of more sensitivity to chemotherapy, the EGFR-mutated cancer cells are eliminated faster than non-mutated cells leading to the shift of EGFR status from positive to negative after chemotherapy." (PMID 32746896, 2020). "Individuals with EGF mutations were shown to have associated isolated recessive renal hypomagnesemia and cancer patients treated with the EGFR inhibitor cetuximab have reduced serum Mg2+ levels that normalize upon therapy withdrawal." (PMID 32706027, 2020).